INS (insulin)
Diseases named in the same sentence as INS in open-access papers (continued):
Sharing a sentence is not in itself a finding about the gene and the disease.
sarcopenia (continued). "Sedentary lifestyles are a primary factor responsible for decreases in skeletal muscle mass and insulin sensitivity, and physical exercise is strongly linked to lower sarcopenia risk, especially in older adults." (PMID 35159148, 2022). "In murine models, increased RBP-4 seems to cause a direct interference of insulin action inside the SM, potentially contributing to sarcopenia." (PMID 34858322, 2021). "In contrast, one study found that endogenous insulin secretion capacity was positively associated with muscle mass, and high HbA1c was associated with the occurrence of sarcopenia in T2DM subjects." (PMID 34722893, 2021). "The fasting insulin combined with the AST/ALT ratio exhibits good diagnostic performance for sarcopenia." (PMID 34956096, 2021). "For contrasting reasons, sulfonylureas and insulin, which favor weight gain, can also increase the risk of sarcopenia, since this can aggravate insulin resistance and related mechanisms involved in the pathogenesis of sarcopenia." (PMID 34440727, 2021). "As for allele frequency, the INS allele of this polymorphism increased the risk of sarcopenia compared to the DEL allele (OR: 1.932; 95%CI: 1.187–3.145)." (PMID 34683186, 2021). "Consonantly in this study, both insulin and c-peptide levels were associated with sarcopenia status, ASMI, and lower limb strength, and were preserved by any of the active interventions but decreased in the standard care group." (PMID 33882026, 2021). "Insulin loss during this period can exacerbate exhaustion of bone marrow cells by unhealthy muscle tissues which results in bone mass loss and sarcopenia." (PMID 33744845, 2021). "The results of the logistic regression analysis showed that the INS/INS genotype of the NFkB1 polymorphism (rs28362491) increased the risk of sarcopenia compared to the other genotypes (OR: 2.943; 95% CI: 1.301–6.654)." (PMID 34683186, 2021). "Sarcopenia status and reduction were associated with blood biomarkers related to muscle metabolism, steroid hormone regulation, insulin-leptin signaling, and tissue oxygenation." (PMID 33882026, 2021). "In conclusion, advanced age, being men, duration of T2DM ≥10 years, on combined OHA and insulin, on <5 types of medications, lower BMI, and low and moderate levels of physical activities were associated with sarcopenia." (PMID 32433712, 2020). "Sarcopenia can cause skeletal muscle mass and strength to decrease, thereby reducing skeletal muscle insulin sensitivity." (PMID 32082422, 2020). "Sarcopenia is associated with a reduction of muscle capillaries and a decrease of insulin sensitivity and inflammation severity, leading to declined mitochondrial biogenesis and function as well as protein synthesis disruption." (PMID 32443396, 2020). "Further studies are necessary to elucidate the age-associated imbalance leading to skeletal muscle loss or the sarcopenia response to insulin sensitivity." (PMID 32178449, 2020). "The composition and amount of dietary fats influence inflammation and insulin resistance —both mechanisms linked to sarcopenia." (PMID 30709690, 2020). "Another possible mechanism is that the decline in insulin sensitivity causes a defect in muscle mass catabolism and muscle quality, resulting in sarcopenia and loss of strength." (PMID 30862906, 2019). "Since skeletal muscle is the main tissue for the insulin-dependent glucose uptake, sarcopenia is associated with the systemic insulin resistance that is a component of metabolic syndrome." (PMID 31882910, 2019). "A recent report examined the association between various parameters of endogenous insulin secretion and sarcopenia evaluated through DXA in patients with type 2 DM." (PMID 30922266, 2019). "All types of exercise improve functional capacity and mitigate risk factors for sarcopenia, including inflammation, oxidative stress, and insulin resistance." (PMID 31271587, 2019).
sarcopenia (continued). "This is negatively linked to ISEM, consistent with the known influence of adipokines on beta cell function through enhancing or inhibiting insulin release, pointing to the dysregulated production of adipokines in sarcopenia associated with obesity." (PMID 30302905, 2018). "Omega 3 fatty acids (FA) attenuate inflammation and age-associated muscle loss, prevent systemic insulin resistance and improve plasma lipids, potentially impacting on sarcopenia." (PMID 29324650, 2018). "A loss of fast twitch fibers, insulin resistance, glycation of proteins, and lipid deposition in muscle cells play important roles in the loss of muscle strength and development of sarcopenia." (PMID 30388779, 2018). "We also identified several miRNAs which have been associated with primary muscular disorders, aged muscle, sarcopenia, response to inflammatory stimuli, dexamethasone treatment or muscular insulin resistance." (PMID 25630602, 2015). "Although muscle mass may reduce sarcopenia risk, excess fat—particularly visceral—may drive cardiometabolic complications via mechanisms like insulin resistance and chronic low-grade inflammation." (PMID 40909453, 2025). "Elevated TG levels might suggest improved insulin sensitivity, benefiting muscle health by enhancing glucose uptake, promoting muscle protein synthesis, and lowering sarcopenia risk." (PMID 40469587, 2025). "In addition, East Asians are characterized by less obesity and insulin secretion compared to Caucasians, suggesting the possibility of increased susceptibility to sarcopenia." (PMID 41228530, 2025). "Additionally, diminished sleep duration and quality impact the regulation of insulin secretion and sensitivity, thereby increasing the risk of sarcopenia." (PMID 40359225, 2025). "These included evaluating the effect of supervised exercise training, or a specific supplement administration, to decrease the risk of sarcopenia after BS, and proposed assessing the levels of myokines, insulin resistance and patients’ quality of life, among other measurements." (PMID 40164918, 2025). "Given the observed positive associations with lean mass, improved insulin sensitivity, and reduced adiposity, promoting adequate ePUFA intake may be a valuable strategy for enhancing sarcopenia and overall health." (PMID 39764565, 2025). "Sarcopenia is caused by complex and interdependent pathophysiological mechanisms, including aging, neuromuscular junction impairment, mitochondrial dysfunction, insulin resistance, lipotoxicity, endocrine factors, oxidative stress, and inflammation." (PMID 38225199, 2024). "While a low BMI and high body fat percentage increase the likelihood of sarcopenia, insulin therapy’s muscle-mass-loss-inhibitory effects may be BMI-independent." (PMID 39058051, 2024). "High levels of the proinflammatory cytokines tumor necrosis factor-α and IL-6 are associated with sarcopenia due to low GS and muscle mass and may exacerbate insulin action." (PMID 39408048, 2024). "Over time, persistent inflammation may render muscles susceptible to sarcopenia by promoting protein degradation, hindering regeneration, disrupting mitochondrial function, and inducing insulin resistance." (PMID 39334732, 2024). "The underlying mechanism may be that sarcopenia affects body functions and then causes metabolic disorders, including imbalance of energy metabolism, heat regulation, insulin sensitivity and amino acid metabolism disorders." (PMID 39027658, 2024). "Furthermore, since skeletal muscle is the major organ for insulin-mediated glucose uptake, sarcopenia has a profound effect on metabolic health, being a risk factor for the development of metabolic disorders such as type II diabetes." (PMID 36678864, 2023). "Although the exact mechanism underlying the relationships between sarcopenia and cardiometabolic disease remains unclear, current experimental and epidemiological evidence suggests that insulin resistance may play an essential role in mediation pathways." (PMID 37403750, 2023).
sarcopenia (continued). "Testosterone, growth hormone, insulin, and thyroid hormones are associated with sarcopenia." (PMID 38089609, 2023). "Skeletal muscle accounts for approximately 80% of insulin‐mediated glucose uptake, and thus the loss of skeletal muscle mass and function related to sarcopenia is the primary defect that directly prompts impaired muscle glycogen synthesis and insulin resistance." (PMID 37403750, 2023). "The loss of lean skeletal mass (sarcopenia) and strength and impaired muscle metabolism, including mitochondrial dysfunction and insulin resistance, are all common consequences of aging with far-reaching effects on the quality of life and the development of chronic diseases." (PMID 36841788, 2023). "Addressing sarcopenia through such modalities may prevent muscle mass, strength and function decline, maintain insulin-stimulated glucose uptake and reduce the risk of TIID and CVD." (PMID 37508325, 2023). "Insulin secretion and impaired insulin signaling may be a primary defect in sarcopenia associated with their prognosis and quality of life in both diabetic and non-diabetic individuals." (PMID 36482911, 2022). "Indeed, impaired action of insulin/IGF-1 signaling is counted among the potential mechanisms underlying the development of sarcopenia, a major phenomenon associated with aging, which is characterized by decreased mass and impaired function of skeletal muscle." (PMID 36198696, 2022). "A number of extra-hepatic factors are involved in the development and progression of NASH (Tilg and Moschen., 2010), and it has been shown that skeletal muscle loss (sarcopenia) and insulin resistance in skeletal muscle promote the progression of NASH via a muscle-liver axis." (PMID 36439272, 2022). "The present study aimed to ascertain whether sarcopenia is associated with the level of fasting insulin and other biomarkers related to insulin or lipid metabolism in diabetic and non-diabetic older individuals." (PMID 36482911, 2022). "Results show that AST/ALT and INS*PA have better diagnostic efficacy for sarcopenia." (PMID 35370985, 2022). "Furthermore, fasting insulin, C-peptide, and leptin were significantly associated with one or more clinical and functional measures of sarcopenia and frailty including total body mass, muscle mass, knee extension strength, gait speed, and physical activity." (PMID 36482911, 2022). "Taken together, a reduced level of endogenous insulin secretion may thus be a risk factor for sarcopenia development in both Japanese and Chinese diabetic elderly." (PMID 36482911, 2022). "Reduced insulin signaling and increased levels of inflammatory cytokines such as interleukin (IL)-1, IL-6, and tumor necrosis factor-alpha have been suggested to be associated with sarcopenia." (PMID 36143016, 2022). "The underlying mechanism of how sarcopenia might affect CAD seemed to be related to insulin resistance." (PMID 36309772, 2022). "In particular, it seems well established that insulin is able to reduce the risk of sarcopenia, while DPP-4i might have a neutral impact on it." (PMID 34440727, 2021). "As higher muscle mass is related to greater insulin sensitivity and lower risk of prediabetes, sarcopenia may be an early predictor of diabetes susceptibility, independently of obesity." (PMID 35111794, 2021). "Sufficient insulin secretion and efficient insulin signaling play a critical role in promoting protein synthesis, maintaining muscle function, and preventing muscle mass loss and sarcopenia." (PMID 33882026, 2021). "In this sense, muscle clock genes regulate the expression of several genes that act on the local metabolism, and a change in these clocks could cause losses in insulin sensitivity and loss of muscle mass, contributing to the development of sarcopenia." (PMID 34948558, 2021).
sarcopenia (continued). "In skeletal muscles, the age-induced decrease in insulin sensitivity is also associated with the development of sarcopenia, a condition that is characterized by a gradual loss of muscle mass which results in decreased muscle strength resulting in fragility and reduced mobility." (PMID 34356299, 2021). "Also, the insulin signaling pathway appears to be involved in this phenomenon, because daf-2 mutants are resistant to the development of sarcopenia and associated declines in motility during aging." (PMID 34211399, 2021). "Older age and sarcopenia are also associated with IMAT accumulation which may reduce insulin sensitivity." (PMID 33001410, 2020). "Results from a cohort study in Chinese sarcopenia patients showed that high levels of the inflammatory cytokines TWEAK and TNF-α were associated with an increased risk of sarcopenia, while the insulin growth factor 1, insulin, and adiponectin were associated with a decreased risk of sarcopenia." (PMID 32054503, 2020). "Meanwhile, increasing accumulation of body fat, especially visceral fat, could increase the risk of muscle protein wasting, systematic inflammation, and insulin resistance, then increasing the risk of muscle mass decline and sarcopenia in older people." (PMID 33198340, 2020). "For example, given the role of skeletal muscle in glucose metabolism, there is growing speculation that sarcopenia could impair insulin sensitivity and several prospective studies have indeed linked sarcopenia with increased incidence of type 2 diabetes." (PMID 31336753, 2019). "Recurrent starvation episodes under conditions of insulin deprivation may predispose patients to sarcopenia through proteolysis and lipolysis." (PMID 30261059, 2018). "The loss of fast twitch fibers, protein glycation, and insulin resistance may all play important roles in the loss of muscle strength, as well as the development of sarcopenia." (PMID 30087866, 2018). "Since muscle is the primary tissue contributing to whole-body insulin-mediated glucose disposal, sarcopenia may be an important causal factor in age-induced insulin resistance and type 2 diabetes susceptibility." (PMID 22421977, 2010). "Therefore, despite the potential muscle wasting effect of insulin resistance with aging, higher circulating amino acids might help reduce the risk of sarcopenia in older adults." (PMID 39544124, 2025). "whereas age-related factors may be associated with changes in sarcopenia and insulin sensitivity." (PMID 40235662, 2025). "Therefore, strategies aimed to reduce plasma phosphate like the use of phosphate binders or reducing intake should be better adjusted or given in combination with insulin sensitizing drugs particularly to those CKD subjects at greater risk of developing sarcopenia." (PMID 36994079, 2023). "However, increased carbohydrate intake could influence inflammation or insulin sensitivity which can, in turn, affect skeletal muscle loss or sarcopenia." (PMID 36501101, 2022). "Weight loss, which is a well-established and somewhat effective lifestyle modification to improve insulin sensitivity, may be associated with a reduction in lean body mass, contributing to sarcopenia, despite temporary improvements in the insulin sensitivity responses." (PMID 32213854, 2020). "However, factors associated with diminished insulin sensitivity with aging are multifactorial, including increased body fat mass, decreased physical activity, increased oxidative stress and inflammation, and sarcopenia." (PMID 32867083, 2020). "Evidence supports therapeutic BCAA supplementation in hypercatabolic conditions such as sarcopenia and hepatic cirrhosis, while suggesting potential adverse metabolic consequences in insulin-resistant or obese individuals." (PMID 42099642, 2026). "Based on this, the benefits of using anti-diabetic medication and insulin in the context of sarcopenia are being studied." (PMID 40725728, 2025).
sarcopenia (continued). "This phenomenon is closely associated with physiological changes linked to aging, such as the progressive decline in muscle mass (sarcopenia), increased visceral adiposity, impaired insulin sensitivity, and hormonal changes." (PMID 39860021, 2025). "The role of insulin in amino acid metabolism can be supported clinically by the studied relation between T2D and sarcopenia." (PMID 40725728, 2025). "Sarcopenia is related to the imbalance of multiple pathways, including oxidative stress, mitochondrial dysfunction, insulin resistance, and protein metabolism." (PMID 40429815, 2025). "Muscle wasting is a major characteristic of CKD-related sarcopenia and is driven by multiple molecular mechanisms related to dysregulated muscle proteostasis, insulin resistance, metabolic acidosis, and excessive muscle inflammation." (PMID 39940262, 2025). "The differences between studies are likely attributable to metabolic changes in older populations, including sarcopenia, body composition alterations, and decreased insulin sensitivity." (PMID 41003141, 2025). "This process aggravates age-related low-grade chronic inflammation and increases insulin resistance, mechanisms that are involved in the onset of sarcopenia." (PMID 40109720, 2025). "In the elderly population, resistance training is widely applied as a primary intervention to counteract sarcopenia, and several studies have also reported beneficial effects on glucose metabolism and insulin sensitivity." (PMID 41357171, 2025). "Exercise interventions provide significant benefits for sarcopenia, cardiorespiratory fitness, insulin sensitivity, and quality of life." (PMID 39982238, 2025). "The etiology and pathogenesis of sarcopenia caused by T2DM are very complex, including increased insulin resistance, impaired function of muscle satellite cells, inflammatory responses in skeletal muscles, and damage to microvessels in skeletal muscles, etc.." (PMID 41561057, 2025). "In older people, therapeutic adjustments require special attention due to factors such as variable intake, polypharmacy, sarcopenia and decreased muscle and liver glycogen stores, which increase their sensitivity to insulin." (PMID 40340929, 2025). "Evidence indicates that middle-aged muscle exhibits aberrant metabolism, impaired insulin sensitivity, and an early, gradual reduction in mass, suggesting that decline begins long before overt sarcopenia." (PMID 41155437, 2025). "Ageing is associated with chronic low-grade inflammation, resulting in reduced muscle protein synthesis and increased resistance to insulin, which both contribute to sarcopenia." (PMID 41476438, 2025). "Myostatin, the first recognized myokine, is an important negative regulator of muscle mass, and isassociated with sarcopenia; it also appears to have a role in glucose homeostasis,increasing insulin resistance." (PMID 41585414, 2025). "Furthermore, unique dietary components within DI-GM, such as fermented dairy products, soybean oligosaccharides, sucrose, and chlorogenic acid, may influence KDM by improving insulin sensitivity, reducing oxidative stress, and promoting muscle protein synthesis, thereby lowering sarcopenia risk." (PMID 40191209, 2025). "This anabolic resistance to insulin contributes significantly to the difficulty in maintaining muscle mass through nutritional interventions alone in conditions such as sarcopenia and cachexia." (PMID 41220691, 2025). "Lifestyle changes are essential for the prevention of MAFLD and sarcopenia, as these strategies address shared pathophysiological mechanisms such as insulin resistance, oxidative stress, and chronic inflammation." (PMID 40429815, 2025). "Sarcopenia can contribute to the onset of T2D by reducing skeletal muscle mass, a major site for insulin-mediated glucose disposal, while sarcopenia is also associated with physical inactivity and frailty, both risk factors for T2D." (PMID 41465555, 2025).